RNU6-1009P (RNA, U6 small nuclear 1009, pseudogene)
Gene: Small nuclear RNA gene on chromosome 12 (64,204,793 to 64,204,899, forward strand). Ensembl gene ENSG00000212298.
Homologues: Orthologues: chimpanzee U6 (100% identical), macaque U6 (91% identical), rat LOC120094561 (67% identical). Paralogues in human: RNU6-266P (78% identical), RNU6-1060P (76% identical), RNU6-1266P (76% identical), RNU6-24P (76% identical), RNU6-672P (76% identical), RNU6-949P (76% identical), RNU6-1024P (75% identical), RNU6-1303P (75% identical), RNU6-19P (75% identical), RNU6-455P (75% identical), RNU6-536P (75% identical), RNU6-573P (75% identical), and 1283 more.